CBX7 (chromobox 7)
Diseases named in the same sentence as CBX7 in open-access papers (continued):
Sharing a sentence is not in itself a finding about the gene and the disease.
gastric tumors (4 papers, 2010 to 2022). "On the other hand, Cbx7 acts as an oncogene in gastric tumors by suppressing p16/CDKN2A and supporting AKT1 signaling pathway." (PMID 36361869, 2022). "By IHC analysis, 25 of 75 (33.3%) paraffin-embedded archival gastric tumor biopsies showed a positive staining for CBX7." (PMID 20723236, 2010). "Compared with normal gastric mucosal tissues, gastric tumor tissues expressed significantly higher positive rate of CBX7 (p = 0.031)." (PMID 20723236, 2010). "Previously, it was reported that CBX7 was highly expressed in gastric tumors and that it may have an oncogenic role similar to other PcG proteins." (PMID 29422082, 2018). "Then, we studied the expression of CBX7 in normal gastric tissues and gastric tumor tissues by IHC." (PMID 20723236, 2010).
lung adenocarcinoma (4 papers, 2021 to 2023). A carcinoma that arises from the lung and is characterized by the presence of malignant glandular epithelial cells. "This study aims to explore the function and underlying molecular mechanisms of CBX7 in lung adenocarcinoma (LUAD) and lung squamous cell carcinoma (LUSC)." (PMID 35646140, 2022). "In addition, lncRNA SNHG7 can also indirectly influence the expression of CBX7 by regulating miR-181 in lung adenocarcinoma." (PMID 34659360, 2021). "Meanwhile, key genes extensively indicated significant prognostic significance, and CBX7, ITGA8, ADRB2, and CAV1 were significant favorable factors for lung adenocarcinoma." (PMID 37123398, 2023). "Similarly, in lung adenocarcinomas, miR-181 overexpression promotes epithelial-mesenchymal transition (EMT) by directly targeting CBX7." (PMID 34659360, 2021). "However, CBX7 and ADRB2 were significantly downregulated in lung adenocarcinoma tumor tissues and may serve as favorable prognostic factors for lung adenocarcinoma (p < 0.05)." (PMID 37123398, 2023).
ovarian clear cell adenocarcinoma (4 papers, 2019 to 2024). A malignant glandular epithelial neoplasm characterized by the presence of clear and hobnail cells. "CBX7 is associated with poor prognosis in ovarian clear cell adenocarcinoma by modulating the level of the tumor necrosis factor-related apoptosis-inducing ligand (TRAIL) and inhibiting apoptosis." (PMID 36361869, 2022). "In ovarian clear cell adenocarcinoma, expression of chromobox homolog 7 (CBX7) portends an ominous prognosis." (PMID 38413558, 2024). "Further,studies have shown high expression of CBX7 in various prostatecancer cell lines and clear cell adenocarcinoma of the ovary." (PMID 32453338, 2020).
pancreatic adenocarcinoma (4 papers, 2010 to 2025). "Loss of CBX7 expression is associated with increasing malignancy grade in pancreatic adenocarcinoma, whereas the maintenance of CBX7 expression correlated with longer survival." (PMID 28030829, 2017). "Reduced expression of CBX7 and PTEN was associated with increased malignancy grade in pancreatic adenocarcinoma, whereas maintenance of CBX7 and PTEN expression showed a trend toward a longer survival." (PMID 28030829, 2017). "In our study, we found that restoration of CBX7 resulted in NF-κB expression, which suggested that the regulation of PTEN/Akt and downstream NF-κB pathways might be one of the important mechanisms underlying CBX7's tumor suppressive role in pancreatic adenocarcinoma." (PMID 28030829, 2017).
liver cancer (3 papers, 2018 to 2022). An epithelial or non-epithelial malignant neoplasm that arises from the liver. "We also examined the expression of miR-181 and CBX7 in the TCGA liver cancer database and explored associations with patient outcomes." (PMID 35867177, 2022). "Besides, higher mRNA expressions of CBX1/2/3/6/8 were significantly associated with shorter OS in liver cancers patients, while higher mRNA expression of CBX7 was significantly related to favorable OS in liver cancer patients." (PMID 30481161, 2018). "In liver cancer, the expression of CBX7 mRNA is the highest in grade I tumors among grade classification of tumor." (PMID 34659360, 2021). "Thus, we focussed on CBX7 as the most likely mediator of miR-181 effects in liver cancer progression." (PMID 35867177, 2022). "Furthermore, increased CBX7 greatly reduced tumour proliferation as measured by PCNA, and one CBX7 target, cyclin E1, which is essential for liver cancer progression, was significantly reduced upon increased CBX7 expression." (PMID 35867177, 2022). "Accumulative evidence has shown that CBX7 content is significantly reduced in liver cancer tissues." (PMID 34659360, 2021). "However, on other hand, higher mRNA expression of CBX7 was correlated with better OS in liver cancers patients." (PMID 30481161, 2018). "Furthermore, CBX7 had been demonstrated to be a liver cancer suppressor." (PMID 35867177, 2022). "Similarly, the mode of action of CBX7 in liver cancer is a continuous one-way pathway." (PMID 34659360, 2021). "Thus, we analysed CBX7 expression in the TCGA liver cancer (TCGA-LIHC) data and found the iClust1 HCCs had significantly lower expression levels of CBX7 than either iClust2 or iClust3 HCCs." (PMID 35867177, 2022). "First, the miR-181/CBX7 axis clearly played a vital role in DEN-induced liver cancer animal models (the DEN model), but this may not always be the case in other liver cancer animal models." (PMID 35867177, 2022).
sarcoma (3 papers, 2021 to 2022). A usually aggressive malignant neoplasm of the soft tissue or bone. "The expression levels of HP1-α/β/γ (CBX1/3/5) and CBX7 were associated with overall survival (OS) in patients with sarcoma, while high expression levels of CBX7 were related to disease-free survival (DFS)." (PMID 34046352, 2021). "In sarcoma, we found that the expression level of CBX7 was downregulated in sarcoma, and that the elevated expression of CBX7 was associated with a better OS and DFS." (PMID 34046352, 2021). "In this subtype of sarcoma, CDKN2A firmly connects to MDM2, CCND1, PIK3CA, CDK4, CBX7, and less firmly to EGFR, and IL-6." (PMID 34359782, 2021).
acute myeloid leukemia (2 papers, 2018 to 2024). Acute myeloid leukemia (AML) is a group of neoplasms arising from precursor cells committed to the myeloid cell-line differentiation. "Cases in which CBX7 is strongly upregulated include gastric cancer, germinal center-derived follicular lymphomas, and acute myeloid leukemia, where it promotes proliferation, suppresses differentiation, and contributes to the self-renewal of stem cells." (PMID 39402138, 2024). "CBX7, for example, is upregulated in acute myeloid leukemia and other malignancies." (PMID 39402138, 2024). "In acute myeloid leukemia, BMI1 is over-expressed, while other genes from the same family, such as CBX6 and CBX7, are down-regulated." (PMID 30574454, 2018). "In particular, high levels of BMI1, an oncogene highly expressed in acute myeloid leukemia and in advanced phases of CML, were connected to a poorer outcome, whereas on the other side a high expression of CBX6 and CBX7 played a favorable role." (PMID 30574454, 2018).
breast tumors (2 papers, 2017 to 2021). "Noteworthily, CBX1 and CBX2 were associated with chemoresistance whereas CBX7 was associated with tamoxifen sensitivity, as well as chemosensitivity in breast tumors." (PMID 29190923, 2017). "Underpinning the biological significance of metabolic roles, CBX2 and CBX7 were found to be the most up‐ and downregulated isoforms, respectively, in breast tumors compared with normal tissues." (PMID 33400401, 2021). "Further, we evaluate the biological and clinical relevance of identified metabolic roles of CBX2 and CBX7 to show that these two isoforms are most differentially expressed in breast tumors and are informative about prognosis and drug sensitivity." (PMID 33400401, 2021). "Reproducibly in both datasets, CBX2 was found to be the most upregulated and CBX7 as the most downregulated isoforms in breast tumors compared with normal tissues." (PMID 33400401, 2021). "We conjectured that CBX2 and CBX7 may modulate growth signaling to induce metabolic reprogramming in breast tumors." (PMID 33400401, 2021). "High level of CBX7 in breast tumors might portend a better response when treated with tamoxifen or chemotherapeutical agents." (PMID 29190923, 2017). "CBX2 and CBX7 are over‐ and underexpressed in a subset of tumor samples; percentage of CBX2 over‐ and CBX7 underexpressing samples increased with breast tumor aggressiveness in both datasets." (PMID 33400401, 2021). "Consistently, genomic data also showed higher amplification frequency of CBX2, not CBX7, in breast tumors." (PMID 33400401, 2021). "Moreover, CBX2 and CBX7 expression (not other isoforms) correlated strongly, but oppositely, with breast tumor subtype aggressiveness and the proliferation markers." (PMID 33400401, 2021).
clear renal cell carcinoma (2 papers, 2022 to 2024). "Similarly, western blot analysis of the protein levels of CBX7 in patient samples with clear renal cell carcinoma from our hospital indicated that CBX7 was decreased in cancer tissues compared to adjacent nontumor (NAT) renal tissues." (PMID 35342353, 2022).
diffuse gastric adenocarcinoma (2 papers, 2020 to 2022). An adenocarcinoma arising from the stomach. "In Cho's gastric dataset, CBX7 was downregulated in diffuse gastric adenocarcinoma (fold − change = −1.656 and P = 9.09E − 05)." (PMID 33344640, 2020).
pancreatic ductal adenocarcinoma (2 papers, 2017 to 2025). An infiltrating adenocarcinoma that arises from the epithelial cells of the pancreas. "A schematic diagram illustrating the molecular mechanism by which DNMT1 regulates the CBX7/ERK axis in pancreatic ductal adenocarcinoma." (PMID 40387566, 2025). "In addition, immunohistochemical analysis the CBX7 and PTEN expression in 74 surgically resected pancreatic ductal adenocarcinoma (PDAC) specimens revealed that CBX7 expression is significantly downregulated in pancreatic ductal adenocarcinoma, compared to normal pancreatic tissues." (PMID 28030829, 2017).
papillary thyroid carcinoma (2 papers, 2014 to 2015). "As far as the papillary thyroid carcinomas are concerned, FOS, FOSB and EGR1 genes were down-regulated, like CBX7, while SPP1, SPINK1 and STEAP1 were up-regulated." (PMID 24865347, 2014).
renal cell carcinoma (2 papers, 2022 to 2023). "The RNF26/CBX7 axis modulated the TNF pathway to promote Renal cell carcinoma proliferation." (PMID 37188171, 2023). "In this study, we performed bioinformatic analysis to show that CBX7 and CBX6 functioned as protective factors with hazard ratios (HRs) less than 1 but CBX8 and CBX4 functioned as risk factors with HRs greater than 1 in renal cell carcinoma." (PMID 35342353, 2022). "Least absolute shrinkage and selection operator (LASSO)-Cox regression analysis with 1000 replications for these eight CBX family members in the TCGA-KIRC dataset further showed that CBX7 might be a key gene related to overall survival (OS) in renal cell carcinoma." (PMID 35342353, 2022).
Stroke (2 papers, 2018 to 2022). Sudden impairment of blood flow to a part of the brain due to occlusion or rupture of an artery to the brain. "Moreover, CBX7 (target of miR-4446), SPRN and STK35 (targets of miR-6721-5p) have also been studied in stroke models." (PMID 35328807, 2022).
thyroid (2 papers, 2014 to 2019). "CBX7 has been associated with thyroid and endometrial cancer." (PMID 30620740, 2019).
Arrhythmia (1 paper, 2026). Any cardiac rhythm other than the normal sinus rhythm. "Thus, in aged myocardium, the benefit of CBX7 knockout arises independent of proliferation, instead aligning with reduced injury, fibrosis, repolarization heterogeneity, and arrhythmia risk." (PMID 41117088, 2026).
astrocytoma (1 paper, 2013). "Among them, the expressions of EZH2 and PHF19 correlated positively with the astrocytoma grades, whereas the expressions of CBX7, CBX6 and EZH1 correlated negatively with astrocytoma grades." (PMID 24260522, 2013). "CBX6, CBX7 and EZH1 shared a similar pattern and correlated negatively with increasing astrocytoma grade, whereas the opposite occurred with EZH2 and PHF19." (PMID 24260522, 2013). "Interestingly, changes in EZH2, PHF19, CBX7, CBX6 and EZH1 occurred progressively as astrocytoma grade increased." (PMID 24260522, 2013).
breast adenocarcinoma (1 paper, 2022). "CBX7 reduces the emergence of breast adenocarcinoma by inhibiting the Wnt/β-catenin pathway via upregulation of the Wnt antagonist DKK-1 expression." (PMID 35464847, 2022).
cerebral cavernous malformation (1 paper, 2024). A disorder characterized by malformations in the structure of the capillaries in the brain. "A novel therapeutic approach for the treatment of cerebral cavernous malformation (CCM) was established through targeting the polycomb repressive complex 1 protein CBX7." (PMID 39402138, 2024).
chronic myeloid leukemia (1 paper, 2024). "Although CBX6 has not been reported to regulate hematopoietic cell fate decisions, both CBX6 and CBX7 are suggested to be tumor suppressors in chronic myeloid leukemia (CML)." (PMID 38426219, 2024).
embryonal carcinoma (1 paper, 2010). A non-seminomatous malignant germ cell tumor characterized by the presence of large germ cells with abundant cytoplasm resembling epithelial cells, geographic necrosis, high mitotic activity, and pseudoglandular and pseudopapillary structures formation. "In contrast, CBX7 could bind to DNMT1 and induce methylation of E-cadherin and other tumor suppressor genes, not including p16, in the embryonal carcinoma cell line Tera-2." (PMID 21060834, 2010).
esophageal adenocarcinoma (1 paper, 2022). A malignant tumor with glandular differentiation arising predominantly from Barrett mucosa in the lower third of the esophagus. "The overexpression of CBX3 (HR = 3.12, p = 0.00028) and CBX8 (HR = 2.27, p = 0.035) mRNAs in esophageal adenocarcinoma patients were significantly correlated with shorter OS, whereas the overexpression of CBX7 mRNA (HR = 0.48, p = 0.039) was significantly correlated with longer OS." (PMID 35464847, 2022).
esophageal squamous cell carcinoma (1 paper, 2024). Esophageal squamous cell carcinoma (ESCC) is a type of esophageal carcinoma (EC) that can affect any part of the esophagus, but is usually located in the upper or middle third. "FOXC1, in turn, promotes esophageal squamous cell carcinoma stem-like properties by transactivating CBX7 and IGF-1R." (PMID 38413558, 2024).
liver fibrosis (1 paper, 2022). "Thus, additional animal models, especially models with chronic liver inflammation and liver fibrosis, may be needed to further explore the miR-181/CBX7 axis in hepatocarcinogenesis." (PMID 35867177, 2022).
lung adenoma (1 paper, 2014). A benign, well circumscribed epithelial neoplasm that arises from the bronchus or the lung parenchyma. "We have recently generated Cbx7-KO mice validating a tumor suppressor role of the Cbx7 gene since these mice developed liver and lung adenomas and carcinomas that were associated with an increased expression of the cyclin E gene." (PMID 25190058, 2014). "These mice develop liver and lung adenomas and carcinomas, which confirms a tumour suppressor role for CBX7." (PMID 25190058, 2014).
Lymphatic Metastasis (1 paper, 2021). Transfer of a neoplasm from its primary site to lymph nodes or to distant parts of the body by way of the lymphatic system. "The patients with lymphatic metastasis and vascular invasion had higher proportion of CBX7 negative expression but lower proportion of CBX7 high expression (P < 0.05)." (PMID 33748425, 2021).
malignant meningioma (1 paper, 2024). "In this study, we uncovered that CBX7 is suppressed in malignant meningioma and CBX7 restoration significantly attenuates meningioma progression and prolongs survival." (PMID 37791390, 2024).
melanoma (1 paper, 2021). A malignant, usually aggressive tumor composed of atypical, neoplastic melanocytes. "In melanoma, the downstream kinase targets of CBX7 are Polo-like kinase 1(PLK1) and cyclin-dependent kinase 1(CDK1), which are related to genome stability." (PMID 34659360, 2021). "Moreover, in melanoma studies, it has been shown that in the presence of CBX7 inhibitors, DNA damage repair is inhibited." (PMID 34659360, 2021).
meningioma (1 paper, 2024). A generally slow growing tumor attached to the dura mater. "iTRAQ-based comparative proteomics indicated that CBX7 restoration inhibits meningioma cell proliferation via reprogramming metabolic flux from glycolysis to OXPHOS." (PMID 37791390, 2024). "Taken together, our discoveries demonstrated that CBX7 restoration reprograms the metabolic flux from glycolysis to OXPHOS in meningioma cells." (PMID 37791390, 2024). "ChIP–qPCR with CBX7 antibody verified the binding of CBX7 at the promoter of USP44 in both meningioma cell lines." (PMID 37791390, 2024). "Through iTRAQ-based proteomics analysis, we found that CBX7 restoration switches the metabolic flux from glycolysis to OXPHOS in meningioma cells." (PMID 37791390, 2024). "As expected, CBX7 restoration significantly impeded the progression of subcutaneous meningioma xenograft in mice." (PMID 37791390, 2024). "In vivo, two xenograft animal models also confirmed the tumor suppressor role of CBX7 during meningioma progression." (PMID 37791390, 2024). "Collectively, these results suggested that CBX7 restoration inhibits cell proliferation and induces G1/S cell cycle arrest in meningioma cells." (PMID 37791390, 2024). "The statistical analysis demonstrated that CBX7 expression negatively correlated with the malignancy grade and Ki-67 index in meningioma." (PMID 37791390, 2024). "Functional studies revealed that CBX7 restoration significantly inhibits the proliferation of meningioma cells." (PMID 37791390, 2024). "The therapeutical effectiveness of targeting the CBX7/USP44/c-MYC/LDHA axis in meningioma patients needs to be further explored." (PMID 37791390, 2024). "Although the details regarding the specific E3 ubiquitin ligase that targets c-MYC protein for degradation remain to be further elucidated, the present study indicates a novel function of the CBX7/USP44/c-MYC pathway in meningioma." (PMID 37791390, 2024). "Nonetheless, we unveiled that CBX7 expression level negatively correlates with c-MYC level in meningioma patients and CBX7 can destabilize c-MYC protein in a proteasome-dependent manner." (PMID 37791390, 2024). "Collectively, these data supported the functional role of the CBX7/c-MYC/LDHA axis during meningioma progression." (PMID 37791390, 2024). "The immunohistology data showed that >80% of grade I tumors exhibited high expression level of CBX7, while this percentage decreased as meningioma histological grade increased." (PMID 37791390, 2024). "CBX7 restoration significantly induces cell cycle arrest and inhibits meningioma cell proliferation." (PMID 37791390, 2024). "We found that CBX7 expression progressively decreases with malignancy grade and neoplasia stage in meningioma and high CBX7 expression predicts a favorable prognosis in meningioma patients." (PMID 37791390, 2024). "In this study, we found that CBX7 is downregulated during meningioma development and high CBX7 expression possesses significant prognostic value in meningioma patients." (PMID 37791390, 2024). "More importantly, the role of the CBX7/USP44/c-MYC/LDHA axis is confirmed in human meningioma tissue samples." (PMID 37791390, 2024). "CBX7 restoration significantly inhibits meningioma cell proliferation and extends the survival of mice bearing orthotopic meningioma xenografts." (PMID 37791390, 2024). "We found that CBX7 restoration dramatically increased the ubiquitin modification level on c-MYC protein in meningioma cells." (PMID 37791390, 2024). "More importantly, the functional role of CBX7 was further confirmed in subcutaneous and orthotopic meningioma xenograft mouse models and meningioma patients." (PMID 37791390, 2024). "Strikingly, CBX7, which was known as an oncogene, was also indicated to be repressed during meningioma progression." (PMID 37791390, 2024).